AFP (alpha fetoprotein)
Diseases named in the same sentence as AFP in open-access papers (continued):
Sharing a sentence is not in itself a finding about the gene and the disease.
tumor (continued). "Patients with higher mRNAsi exhibited significantly poorer tumor differentiation (P < 0.0001), increased vascular invasion (P = 0.022), and elevated AFP levels (P = 0.021)." (PMID 41050691, 2025). "AFP served as the target analyte, while the other tumor markers (CEA and CA19‐9) were used as controls." (PMID 40693399, 2025). "CD90(+) CTCs, DCP, and AFP showed significant alterations corresponding to tumor size changes, whereas EpCAM(+) CTCs only increased in progressive cases." (PMID 40940925, 2025). "This study focuses on the effect of the AFP-tumor size ratio (ATR) on the prognosis of patients with HCC and investigates the correlation between the ratio and the degree of tumor malignancy." (PMID 40857604, 2025). "For tumor markers, AFP was evaluated in 747 subjects, CA 19-9 in 740 subjects, CEA in 739 subjects, and PSA in 742 subjects." (PMID 40078230, 2025). "The following factors were analyzed in detail, including preoperative AFP level, tumor diameter, multiple tumors, MVI and PVTT." (PMID 41200181, 2025). "While other tumour markers (AFP, CA19 9 and CEA) were obtained, CA 125 testing, an epithelial ovarian tumour markers was not ordered." (PMID 41399424, 2025). "Tumor marker analysis indicated a significant decrease in AFP levels in the high AFP marker group and PIVKA-II levels in the high PIVKA-II marker group, highlighting the potential effectiveness of CIK therapy in high-risk patients." (PMID 40002160, 2025). "Nevertheless, some authors found that a free surgical margin >10 mm is only necessary in more aggressive HCC, defined as in preoperative circulating tumor cells >1 for patients with a baseline AFP > 200 ng/mL and in cases with MVI+." (PMID 40507240, 2025). "A tumor screening was performed using renal ultrasound and alpha-fetoprotein (AFP) testing as a measure of tertiary prevention, given that hyperplasia represents a risk factor for the patient." (PMID 40959375, 2025). "In the test set, significant differences were observed in AFP levels and tumor diameter between the two groups (p < 0.05)." (PMID 40357300, 2025). "This study identified tumor size, CAA, history of HBV infection, TB, AFP, and postoperative ALT as independent risk factors (P < 0.05) influencing early postoperative recurrence." (PMID 40458724, 2025). "Liver and renal function tests remained within normal limits, as well as tumor markers, including alpha-fetoprotein (AFP), carbohydrate antigen 19-9 (CA 19-9), carcinoembryonic antigen (CEA), and prostate-specific antigen (PSA)." (PMID 40893811, 2025). "Three months post-treatment, imaging revealed tumor regression (from 100 mm to 60 mm) and significant decline in tumor markers (AFP 1550–110 ng/mL; PIVKA-2 32,600 to 79 AU/mL)." (PMID 40500480, 2025). "The metroticket 2.0 classification represents the sum of the tumor diameter and the number of tumor lesions together with the AFP value." (PMID 41375030, 2025). "Her tumor markers, including alpha-fetoprotein (AFP), carcinoembryonic antigen (CEA), and carbohydrate antigen (CA) 19-9, were within normal limits." (PMID 40583924, 2025). "Serum tumor markers showed normal alpha-fetoprotein (AFP) and elevated beta-human chorionic gonadotropin (β-hCG)." (PMID 40688995, 2025). "Previous studies identified high AFP level, tumor size > 5 cm and intratumor necrosis as independent predictors of VETC, consistent with our clinical-radiologic and DLR nomogram model." (PMID 41428280, 2025). "Based on this, we will conduct a multicenter cohort study to further validate the model’s efficacy and accuracy, while incorporating postoperative tumor markers (AFP and CA125) to test its predictive performance." (PMID 40900791, 2025). "Post-treatment MRI demonstrated tumor shrinkage to 11.7 × 9.8 × 11.5 cm and decreased enhancement; AFP decreased to 649 ng/mL." (PMID 40934000, 2025).
tumor (continued). "Its expression correlated with tumor presence, age, sex, AFP level, and histological grade.To visualize the relationships between CLGN expression and clinicopathological features, a Sankey diagram was generated." (PMID 41395613, 2025). "Laboratory tests, including complete blood count, liver and renal function tests, and tumor markers (including alpha-fetoprotein [AFP]), were all within normal ranges." (PMID 40978045, 2025). "Patients with NPC2 downregulation express higher alpha-fetoprotein, a wide range of tumor types, vascular infiltration, later pathological stage, and lower survival." (PMID 40302802, 2025). "Patients with elevated tumor markers of AFP ≥ 10 ng/ml or PIVKA-II ≥ 30 mAU/ml before EBRT were enrolled." (PMID 40392828, 2025). "The largest weighted factors in MoRAL-AI were age, tumor size, age, and serum levels of the AFP and prothrombin time." (PMID 39941182, 2025). "At that time, the levels of serum tumor markers were elevated with an AFP level of 550 ng/ml, a β-HCG level of 1,826 IU/l and a lactate dehydrogenase (LDH) level of 1,313 U/l." (PMID 40697355, 2025). "The subsequent introduction of sintilimab-based chemo-immunotherapy resulted in significant tumor regression and a marked reduction in serum AFP levels." (PMID 41235014, 2025). "The laboratory investigations revealed significantly elevated tumor markers, including AFP at 14.21 ng/mL, CEA at 46.91 ng/mL, and CA19–9 at 56.29 ng/mL (all above the reference ranges)." (PMID 40909950, 2025). "Luo’s research confirmed that among the various combinations of three parallel detections of BCa tumor markers, the sensitivity of AFP + CEA + CA153 was the highest, whereas the AUC of CEA + CA125 + CA199 was the highest." (PMID 40158122, 2025). "Established factors favoring HCC recurrence include microvascular invasion and high alpha-fetoprotein (AFP) levels, along with tumor numbers and size." (PMID 40557335, 2025). "Immediately before starting treatment for HCC, tumor markers were markedly decreased (alpha-fetoprotein, from 3098 to 361 ng/mL; des-gamma-carboxy prothrombin, from 2083 to 47 mAU/mL)." (PMID 40696641, 2025). "Patients in the low-risk or A subgroup, characterized by tumor burdens within the up-to-11 criteria, a Child–Pugh score of 5–6, a unilobar tumor location, and serum AFP levels < 400 ng/mL, will likely derive the greatest benefit from TACE." (PMID 40075741, 2025). "Studies have shown that tumor markers such as AFP, CEA, and CA199 are not only related to the diagnosis of HAS, but also to the prognosis of patients." (PMID 40235542, 2025). "Research has unveiled that LINC01296 is significantly increased in HCC, and is closely related to alpha-fetoprotein level, tumor size, and tumor node metastases (TNM) stage." (PMID 39901673, 2025). "BMC showed elevated tumor markers with higher AFP (15,125.0 vs. 48.4 ng/mL, p = 0.03) and PIVKA-II levels (3,556.6 vs. 69.4 mAU/mL, p < 0.01)." (PMID 40656560, 2025). "Tumor markers, such as AFP and DCP were instrumental in evaluating systemic therapy efficacy and guiding surgical decision-making." (PMID 40500480, 2025). "Serum tumor markers such as alpha-fetoprotein (AFP), beta-human chorionic gonadotropin (β-HCG), and lactate dehydrogenase (LDH) play an indispensable role in the diagnosis, staging, and follow-up of TGCTs." (PMID 41527642, 2025). "In policy, continued alignment of allocation rules with tumour biology is essential, incorporating AFP- and DCP-anchored thresholds, response-weighted exceptions, and harmonised LI-RADS imaging language across jurisdictions." (PMID 41301037, 2025). "Regarding tumor markers, AFP demonstrated a specificity of 88%, and β-hCG showed a specificity of 90%." (PMID 41000187, 2025). "While conventional measures like tumor size, AFP, or ALBI grade offer limited prognostic value, radiomics captures multidimensional liver and tumor characteristics that are not discernible by routine imaging." (PMID 40870941, 2025).
tumor (continued). "There was a moderate rise in tumor marker alpha-fetoprotein, which went from 223 to 310 ng/mL within one month." (PMID 40426891, 2025). "Tumor markers, including alpha-fetoprotein (AFP), carcinoembryonic antigen (CEA), and CA 19-9, were within normal limits; however, CA-125 was modestly elevated at 142 U/mL." (PMID 41426782, 2025). "Serum tumor markers like CA19-9, CEA, and AFP show associations with invasiveness but offer modest accuracy (AUC ≈ 0.60–0.70) when used separately." (PMID 41331584, 2025). "Proinflammatory cytokines and tumor markers (AFP, CEA, CA19-9, CA125, and CA15-3) were quantified via ELISA." (PMID 41011277, 2025). "We found that only 2 factors, ablation margins and AFP level, were independent predictors of tumor recurrence." (PMID 40094011, 2025). "From the perspective of unresectable HCC, the tumor size reduction rate and AFP decline ratio, to some extent, reflect the technical and oncological response to unresectability." (PMID 40934000, 2025). "CS2 was found to have higher serum levels of AFP, longer PT, and larger tumor volume when compared with CS1." (PMID 40771801, 2025). "AFP is the tumor marker with the highest level of evidence for HCC and has been extensively studied in relation to the efficacy of ICIs." (PMID 40447887, 2025). "Xu has suggested that the accuracy of the radiomic model in predicting MVI outperforms the clinical logistic regression model based on AST, tumor size, and AFP (AUCs in the validation cohort were 0.750 and 0.648, respectively)." (PMID 41040508, 2025). "The MoRAL-AI model, which uses a deep neural network, incorporates variables such as tumor diameter, AFP, and PIVKA-II." (PMID 40629061, 2025). "High AFP levels (typically > 400 ng/mL, especially > 1000 ng/mL) are significantly associated with MVI, incomplete tumor capsule, intrahepatic dissemination, and distant metastasis." (PMID 41463179, 2025). "While residual tumor cells were observed in the gastric tumor, contrary to the liver tumors, both AFP and SALL4 were positive." (PMID 40657563, 2025). "Long-term surveillance is planned, including annual scrotal ultrasound and AFP measurement until puberty, to monitor for tumor recurrence and assess testicular function." (PMID 41255769, 2025). "In this study, we explore the clinical potential of AFP quantification from cell-free DNA (cfDNA) and circulating tumor cells (CTCs) using a novel bead-based liquid biopsy platform." (PMID 41002319, 2025). "Serum tumor markers further reflected a dominant hepatocellular component, with a significantly elevated AFP level of 100 ng/mL, while CA 19-9 and CEA remained within normal limits." (PMID 40843884, 2025). "Significant intergroup differences existed in tumor diameter, AFP, GGT, and differentiation grade (P < 0.05)." (PMID 41237121, 2025). "Tumor markers (alpha-fetoprotein and protein induced by vitamin K absence or antagonist-II) returned to normal after three cycles, and imaging demonstrated significant shrinkage of both the primary tumor and the lymph nodes." (PMID 41415330, 2025). "Tumor marker analysis showed a mildly elevated alpha-fetoprotein (AFP) level of 14 ng/mL and carbohydrate antigen 19-9 (CA 19-9) of 56 U/mL, while carcinoembryonic antigen (CEA) was not reported." (PMID 40843884, 2025). "The liver function tests and tumor markers were within normal limits, with the alpha-fetoprotein level at 1.38 ng/mL." (PMID 40722538, 2025). "Pretreatment factors such as the Child–Pugh score, tumor burden (up-to-11 criteria), bilobar tumor involvement, and serum alpha-fetoprotein (AFP) levels were analyzed." (PMID 40075741, 2025). "Decline ratios of tumor size and AFP during HAIC + bevacizumab + sintilimab conversion therapy were robust and independent predictors of 1-year postoperative recurrence in HCC." (PMID 40934000, 2025). "Routine tumor markers like AFP, HCG and LDH are usually within normal ranges, and hormone levels remain stable." (PMID 40832615, 2025).
tumor (continued). "Commonly used tumor markers such as beta-hCG and AFP, along with the initial International Federation of Gynecology and Obstetrics (FIGO) stage, can help assess treatment response, guide follow-up, and predict overall survival (OS)." (PMID 40310417, 2025). "In this study, six patients were identified as being high-risk for recurrence based on baseline tumor size ≥ 5 cm, multiple tumor lesions, metastasis, or baseline AFP ≥ 200 ng/ml." (PMID 40186764, 2025). "Early changes in tumor markers, AFP and des-gamma-carboxy prothrombin (DCP), after Dur/Tre introduction have been reported to be a useful biomarker for predicting objective response and clinical prognosis in Dur/Tre therapy." (PMID 40282450, 2025). "In contrast, the tumor in this case exhibited eosinophilic cytoplasm, partial AFP positivity, and HepPar-1 positivity, arguing against CCC." (PMID 40919162, 2025). "Among the tumor markers evaluated, various AFP thresholds were considered, and a cut-off value of 1000 ng/mL was selected based on its strongest association with EHR in our dataset (AUC 0.591)." (PMID 40361344, 2025). "In the high-tumor-marker group divided by post-treatment AFP levels (>10 ng/mL), the median AFP levels significantly decreased from 15.3 ng/mL to 1.3 ng/mL after treatment (p = 0.002), while PIVKA-II levels showed no significant change (p = 0.307)." (PMID 40002160, 2025). "Consistent findings were observed in the TCGA‐LIHC and CHCC cohorts, where high DUSP9 expression was associated with adverse clinicopathological features, including high serum AFP and poor tumour differentiation." (PMID 41383134, 2025). "During laboratory investigations, tumor markers such as AFP, HCG, and LDH were within the normal ranges." (PMID 40832615, 2025). "The conventional tumor markers alpha-fetoprotein (AFP) and des-gamma-carboxy prothrombin (DCP) have limitations in reflecting therapeutic responses and clinical status efficiently due to their non-specificity." (PMID 40940925, 2025). "Of these patients, 89% were men, 67% were positive for hepatitis B virus (67%), 92% had Child–Pugh class A (score 5–6) liver function, 64% had bilobar tumor involvement, 72% had serum AFP concentrations < 400 ng/mL, and 55% were within the up-to-11 criteria." (PMID 40075741, 2025). "A weak positive correlation was seen between CEA and CA19-9 (r = 0.40), whereas correlations between these tumor markers and AFP, or between the tumor markers and inflammatory indices, were generally negligible." (PMID 40823085, 2025). "Other variables such as age, sex, HBV infection, AFP level, tumor size, pathological grade, differentiation, and resection margin did not demonstrate significant associations with OS in this cohort (p > 0.05)." (PMID 40226357, 2025). "This cross-sectional study compared tumor marker levels (AFP, CA 19-9, CEA, PSA) among 750 adult males: 250 CC smokers, 250 any HTP users, and 250 quitters." (PMID 40078230, 2025). "The mean alpha-fetoprotein (AFP) value was 637.4 ± 316.5 ng/mL, tumor maximum diameter was 2.73 ± 0.27 cm, and tumor number was 2.19 ± 0.40." (PMID 39873460, 2025). "The training set was used to evaluate prognostic factors and to develop an easily applicable ATSI (AFP and Tumor Shape Irregularity) score, which was verified in the validation set." (PMID 39714631, 2025). "The analysis of tumor-related mechanisms indicates that tumor cells can secrete various tumor markers, including cancer antigens, alpha-fetoprotein, and tissue polypeptide antigens." (PMID 40556659, 2025). "Serum tumor markers were as follows: alpha-fetoprotein (AFP), 8.51 ng/mL; carcinoembryonic antigen (CEA), 5.79 ng/mL; neuron-specific enolase (NSE), 34.40 ng/mL; and pro-gastrin-releasing peptide (ProGRP), 76.50 ng/mL." (PMID 41438978, 2025).
tumor (continued). "In summary, the independent risk factors for mortality in HCC patients following radical resection include PS score, tumor number, maximal tumor size, ES classification, microvascular invasion, resection margin thickness, AFP, AST, and GGT." (PMID 41180318, 2025). "Circ_0009910 demonstrated significant diagnostic accuracy (area under the curve [AUC] = 0.90), effectively differentiating HCC from controls and showing a correlation with tumor size, metastasis, and alpha-fetoprotein (AFP) levels (p < 0.05)." (PMID 40429981, 2025). "AFP correlates with several tumor target proteins for immunotherapy, including VEGFR and epithelial cell adhesion molecule (EpCAM)." (PMID 39714631, 2025). "The process typically begins with serum biomarkers, with AFP being the most widely used for assessing tumor burden and recurrence." (PMID 40136353, 2025). "This study aims to evaluate the efficacy of intraoperative radiotherapy combined with drug therapy (IORT-DT) in treating hepatopancreatic tumours, focusing on serum tumour markers such as AFP and CA19-9." (PMID 40951893, 2025). "Following matching, the two groups were well balanced in terms of age, sex, BCLC stage, HBV status, tumor diameter and number, liver function parameters, and AFP levels." (PMID 41383585, 2025). "The top 5 most important variables in the model were identified as tumor max length, timing of hepatectomy, AFP level, MVI, and differentiation grade." (PMID 39832130, 2025). "Age, ECOG, ALBI grade, AFP, tumor burden, and radiologic pattern independently predicted OS in the multivariate analysis." (PMID 41199230, 2025). "Conversely, factors such as BCLC-C (HR=2.833, P=0.027), exceeding the up to 7 criteria (HR=2.304, P=0.017), tumor diameter over 5 cm (HR=2.194, P=0.017), PVTT (HR=1.889, P=0.047), and AFP over 400 ng/ml (HR=1.787, P=0.047) were linked to shorter survival." (PMID 40376592, 2025). "Laboratory workup revealed elevated HBV DNA—3.21×106 IU/mL—and tumor markers, including alpha-fetoprotein (AFP) 32,982 ng/mL and des-gamma-carboxy prothrombin (DCP, also known as PIVKA-II) >30,000 mAU/mL." (PMID 40534866, 2025). "For example, the presence of portal vein invasion, AFP levels, and favorable tumor characteristics are critical for predicting patient survival outcomes." (PMID 41515610, 2025). "The results showed that tumor size, CAA, history of HBV infection, TB, AFP, and postoperative ALT were independent risk factors for early recurrence after hepatectomy for HCC (P < 0.05)." (PMID 40458724, 2025). "Laboratory investigations showed mild elevation of CA-125 at 51 U/mL, with all other tumor markers, including alpha-fetoprotein (AFP) and human chorionic gonadotropin (hCG), within normal limits." (PMID 40007914, 2025). "Calcium and phosphorus levels were within normal ranges, and tumor markers, including alpha-fetoprotein (AFP) and beta-human chorionic gonadotropin (β-hCG), were also normal." (PMID 41427451, 2025). "Tumor-specific biomarkers such as AFP, β-HCG, urinary catecholamines, ferritin, and LDH remain the primary diagnostic tools in pediatric oncology because they provide tumor-type–specific information that directly guides clinical evaluation." (PMID 41515549, 2025). "Beyond miRNAs, extracellular vesicle-associated miR-10b has been reported to show strong diagnostic performance for lung AdCa, achieving an AUC of 0.998 when compared with established serum tumor markers, including AFP, CEA, CYFRA21-1, NSE, and others." (PMID 41573685, 2025). "Some patients exhibited varying degrees of tumor shrinkage or stability, and significant reductions in serum AFP levels were observed in some cases." (PMID 40432108, 2025). "The initial workup for patients with a suspected testicular mass requires measurement of serum tumor marker levels, including alpha-fetoprotein (AFP), β-human chorionic gonadotropin (β-HCG), and lactate dehydrogenase (LDH)." (PMID 41154418, 2025).